CD24 (CD24 molecule)
Diseases named in the same sentence as CD24 in open-access papers (continued):
Sharing a sentence is not in itself a finding about the gene and the disease.
breast cancer (continued). "For the first time, breast cancer-initiating cells were isolated based on the expression of unique cell surface antigens, which include epithelial specific antigen (ESA) and CD44, but not CD24." (PMID 29258583, 2017). "However, MDA-MB-231 cells are mesenchymal-like breast cancer cells, and majority of them express high levels of CD44 protein and are CD24 negative." (PMID 26973433, 2016). "Breast cancer stem cells express high CD44 and are negative for CD24." (PMID 27029061, 2016). "Moreover, a large proportion of DTCs in breast cancer patients display stem cell-like features, such as ALDH1 positivity or presence of CD44 and absence of CD24." (PMID 24099325, 2013). "A low proportion of breast cancer cells present in LNs may also result in the absence of specific binding with CD326 monoclonal antibody and in turn, the accuracy of detecting CD44+CD24-/low cell contents in SLN was reduced." (PMID 23046710, 2012). "In a recent study related to our work, an identical epigenetic state in the promoter region of the CD24 gene has been observed between interconvertible CD24-positive and negative subsets of CD44+ breast cancer cells, indicating that transcriptional permissiveness is a general phenomenon." (PMID 20730114, 2010). "Although the MCF-7 cell line has a luminal epithelial-like phenotype and lacks a CD44+/CD24- subpopulation, we obtained MCF-7-14 cells of opposite migratory and invasive capabilities from MCF-7 cells and developed a novel model for breast cancer metastasis without requiring constitutive EMT." (PMID 20696077, 2010). "The potential existence of a stem cell-like cell in breast cancer was shown by Al-Hajj and colleagues, who identified a putative breast tumor stem cell-like population that is defined by the presence of CD44 and absence of CD24." (PMID 19589136, 2009). "This phenotype seems to be conserved during the carcinogenesis process and thus is an important tool to study breast cancer progression, however, it is limited by the great cellular heterogeneity of the CD44+/CD24-/low/lin-population, which probably does not contain solely bona fide CSCs." (PMID 19555472, 2009). "Further, we downloaded RNA‐Seq data from breast cancer patients from TCGA‐breast cancer database and found that the expression level of SPRY4‐IT1 was significantly higher in patients with CD44+/CD24‐ breast cancer (n = 237) than those without CD44+/CD24− (n = 872)." (PMID 31736268, 2020). "In breast cancer, tumor cells capable of forming tumors in immunocompromised mice (i.e., CSC by a functional definition) are identified by the expression of either the enzyme aldehyde dehydrogenase (ALDH) and/or the CD24−/CD44+ phenotype, representing two largely non-overlapping cell populations." (PMID 30788286, 2019). "All sphere and monolayer derivative cell models investigated in this report exhibit a unique CD24−/CD44+ marker distribution, although only the S2N spheres were highly tumorigenic at low inoculation cell numbers in vivo (confirmed in 2 more primary breast cancer cell models, data not shown)." (PMID 23042145, 2012). "However, transgenic overexpression of SLUG in the luminal type breast cancer cell line, MCF-7, generated cells with a CD44+/CD24+ phenotype, suggesting that basal cell types but not luminal cell types are susceptible to EMT associated acquisition of CD44+/CD24- phenotype." (PMID 20691079, 2010). "Furthermore, the complex interplay identified between the CD79A+CD24-PANCK+-BCSCs subpopulation and exhausted CD8+ T cells not only offered an avenue for improving prognosis in breast cancer but also emphasized the importance of breast cancer stem cells in the immunosuppressive microenvironment." (PMID 38066053, 2023). "To investigate whether lncRNAs involved in regulating breast cancer stem cell characteristics, we utilized microarray analysis to compare lncRNA expression profiles between non-BCSCs (CD44−/lowCD24+ cells) and BCSCs (CD44+CD24−/low mammospheres) from MCF7 cells." (PMID 34715882, 2021).
ovarian carcinoma (187 papers, 2003 to 2025). A malignant neoplasm originating from the surface ovarian epithelium. "sEVs released from ovarian cancer cells, which carry markers such as CD24 and EpCAM, hold potential for use in diagnostic applications." (PMID 40008006, 2025). "Since CD24 expression was reported to be associated with CSC-like phenotypes in ovarian cancer, cell cycle, colony formation ability (CFA), and drug resistance were investigated." (PMID 38360723, 2024). "Overexpression of CD24 and EpCAM in ovarian cancer cells is associated with poor prognosis and drug resistance." (PMID 38796525, 2024). "Our previous study demonstrated that CD24 expression was associated with the CSC phenotypes of ovarian cancer cells, such as tumourigenesis, chemoresistance and stem‐related gene overexpression." (PMID 38030594, 2024). "CD24-miR-130a/301a-CDK19 signaling axis was associated with CSC-associated phenotypes in ovarian cancer cells." (PMID 38360723, 2024). "For instance, CD24 and epithelial cell adhesion molecule (EpCAM) were found to be highly expressed in tumor-derived exosomes and were thus associated with ovarian cancer development." (PMID 37215442, 2023). "CD24 expression is also associated with the development, invasion, and metastasis of ovarian cancer." (PMID 36980210, 2023). "CD24 is a glycosylphosphatidylinositol linked molecular which expressed in diverse malignant tumor cells, particular in ovarian carcinoma cells and ovarian carcinoma stem cells." (PMID 37359556, 2023). "They found that EV-associated EpCAM and CD24 were significantly higher in the ovarian cancer patients than in controls." (PMID 31212643, 2019). "For example, in patients with ovarian cancer, CD24 expression is independently associated with an increased metastatic potential and a decreased survival." (PMID 30551640, 2018). "It has been found in pseudo-stratified, transitional and simple epithelia on the basolateral surfaces and has been identified as a cargo protein in exosomes.CD24 is recognized as a cancer marker and is associated with poor prognosis of ovarian carcinomas." (PMID 28851367, 2017). "CD24 is a mucin-type glycosylphosphatidylinositol-linked cell surface protein that is expressed in developing or regenerating tissue, and in ovarian cancer and hepatocellular carcinoma." (PMID 25212506, 2014). "Moreover, CD24 expression was observed in ovarian cancer tissue sections, and was associated with metastasis into distant lymph nodes and the peritoneal cavity." (PMID 38791431, 2024). "In addition, analyses using KM plotter and ROC plotter presented that the overexpression of CD24 or MET in ovarian cancer patients was associated with resistance to platinum‐based chemotherapy." (PMID 38030594, 2024). "To validate and test our hypothesis, we analysed the CD24‐associated expression of miRNAs in primary ovarian cancer cells and the Caov‐3 cell line." (PMID 38030594, 2024). "Additionally, higher levels of proteins in ovarian cancer-derived exosomes that have diagnostic potential include CD24, CRABP2, MUC16, MSLN, soluble form of activated leukocyte cell adhesion molecule, and soluble E-cadherin." (PMID 38796525, 2024). "Furthermore, the cytoplasmatic expression of CD24 is associated with poor overall survival in ovarian cancer, thereby CD24−CD44+ cell population is a potential indicator on drug resistance." (PMID 37919766, 2023). "Interestingly, the cytoplasmatic expression of CD24 is associated with poor overall survival in ovarian cancer, whereas CD24−CD44+ cells are an indicator of drug resistance." (PMID 33260974, 2020). "Low CD24 expression is associated with increased relapse-free survival for ovarian cancer patients." (PMID 32937961, 2020). "In addition, significantly increased expression levels of EV-associated CD24, EpCAM, and CA-125 were found in ovarian cancer patients compared to healthy patients." (PMID 31212643, 2019).
ovarian carcinoma (continued). "CD24 is recognized as a tumor marker and is associated with poor prognosis of ovarian carcinomas." (PMID 24460816, 2014). "As a small heavy glycosylated antigen that overexpressed in ovarian carcinoma, CD24 expression is associated with the development, invasion, metastasis of cancers, as well as the immune evasion, which also gained increasing interest in the ovarian cancer therapy field." (PMID 37359556, 2023). "Potent synergy by blocking CD47/SIRPα and CD24/Siglec-10 pathways, enhances macrophage phagocytosis and anti-tumor immune responses; reduces tumor growth in ovarian cancer models." (PMID 40330466, 2025). "CD24+ ovarian cancer cells display stem-like properties, and they are considered as surface markers for ovarian cancer stem cells." (PMID 40486886, 2025). "Ovarian cancer cells, delineated from a homogenous cell line and stratified based on CD24 expression, demonstrate a dichotomy in their therapeutic responses." (PMID 40486886, 2025). "CD24+ ovarian cancer cells have self-renewal, quiescence, and chemotherapy resistance properties and are enriched with stemness-related genes, e.g., Nestin, Bmi-1, and Oct4." (PMID 39967908, 2025). "On the other hand, several studies have identified CD24 as an ovarian cancer stem cell marker, which is pivotal in ovarian cancer progression and metastasis." (PMID 40783744, 2025). "Research focused on epithelial cell adhesion molecules and CD24 in exosomes produced from ovarian cancer has led to a novel option for the early diagnosis of ovarian cancer." (PMID 40612948, 2025). "This microfluidic approach was employed for the multiplexed detection of blood-based ovarian cancer from three different exosomal tumor markers, such as CA-125, EpCAM, and CD24." (PMID 40277517, 2025). "Multiple preclinical studies have demonstrated that CD24 monoclonal antibodies can effectively inhibit the proliferation of cancer cells, including breast and ovarian cancers." (PMID 41354057, 2025). "Both CD47 and CD24 are overexpressed in various cancers, including ovarian cancer, where they deliver “don’t eat me” signals to macrophages, preventing the immune system from effectively eliminating tumor cells." (PMID 40330466, 2025). "We previously reported that CD24‐high ovarian cancer cells showed CSC phenotypes, such as tumourigenicity, chemoresistance and stemness‐related gene overexpression." (PMID 38030594, 2024). "The expression fold changes of CD24, MET and miR‐181a in the CD24‐high population to the CD24‐low population showed a similar trend to those of primary ovarian cancer cell clones." (PMID 38030594, 2024). "Our miRNA transcriptome analysis showed that 94 miRNAs were up or down-regulated in a CD24-high clone from an ovarian cancer patient compared to a CD24-low one." (PMID 38360723, 2024). "CD24 serves as a CSC marker for ovarian cancer and regulates the expression of miRNAs, which are regulators of CSC phenotypes." (PMID 38360723, 2024). "miR-130a and 301a were positively correlated in expression with CD24 in ovarian cancer patient tissues and negatively correlated with CDK19." (PMID 38360723, 2024). "Detection of a panel of biomarkers (EGFR, CA125, EGFR2, folate receptor α, CD9, CD24, and EpCAM) in circulating exosomes not only identified ovarian cancer patients from control subjects but also distinguished between early- and advanced- stage ovarian cancer." (PMID 38796525, 2024). "CD24 is a surface receptor linked to downstream networks, a cancer stem-like cell (CSC) marker for ovarian cancer, and induces miRNA expression." (PMID 38360723, 2024). "We analyzed single-cell data from ovarian cancer patients, focusing on cells enriched for the epithelial cancer cell markers CD24+ and EPCAM+." (PMID 39546568, 2024). "In the third generation of CD24-CAR NK cells designed to treat ovarian cancer, it was discovered that both original tumor cells and CD24+ ovarian cell lines were specifically eliminated by the CD24-NKCAR cells." (PMID 38279998, 2024).
ovarian carcinoma (continued). "A strong CD24 presence also coincided with epCAM, a known marker of cancer, in EVs from an ovarian cancer cell line, which confirmed that the strong expression of CD24 was indeed tumor-derived." (PMID 38473976, 2024). "In our miRNA transcriptome and putative target genes analyses, miR‐181a was downregulated in CD24‐high ovarian cancer cells compared to CD24‐low and predicted to bind to CD24 and MET 3'UTRs." (PMID 38030594, 2024). "In ovarian cancer, the CD24-Siglec-10 axis has been shown to mediate antitumor immunity and has strong potential for therapeutic intervention." (PMID 39432076, 2024). "This study demonstrated that CD24 upregulated MET expression via the Src‐mediated downregulation of miR‐181a in serous types of ovarian cancer cells, which contributed to cellular quiescence‐like state and chemoresistance." (PMID 38030594, 2024). "For miRNA transcriptome analysis, two primary ovarian cell clones with CD24-low (CD14.2) and CD24-high (C4) expression were obtained from an ovarian cancer patient." (PMID 38360723, 2024). "On the other hand, despite the continued ambiguity of the relationship between CD24 expression and CSC phenotypes in ovarian cancer, CD24 expression correlated with CSC phenotypes such as tumorigenesis and drug resistance." (PMID 38360723, 2024). "Increased expression of CD24 and MET, markers for cancer stem‐like cells (CSCs), are each associated with ovarian cancer severity." (PMID 38030594, 2024). "CD24-positive population enriched from an ovarian cancer patient showed stemness-related gene overexpression, resistance to cisplatin, and tumor initiation." (PMID 38360723, 2024). "CD24 has shown elevated levels in several cancers like breast, prostate, pancreatic, and ovarian cancers." (PMID 38881902, 2024). "Our previous study demonstrated that CD24‐positive ovarian cancer cells exhibited tumourigenicity in a mouse model and showed chemoresistance." (PMID 38030594, 2024). "A different study discovered that the genes GATA3, CD24, and Siglec-10 are substantially expressed in the tissues and cells of ovarian cancer (OC)." (PMID 38279998, 2024). "According to our results, CD24 expression increased G0/G1 phase cell population in ovarian cancer, which seemed to be mediated by decreased CDK19 expression and RNA synthesis." (PMID 38360723, 2024). "It has been shown that the CD24‐induced proliferation and invasiveness in ovarian cancer were dependent on the activation of PI3K/Akt, NF-κB and ERK." (PMID 37919766, 2023). "The nPLEX assay was able to distinguish between exosomes from ovarian cancer patients with elevated protein expression of EpCAM and CD24 in comparison with non‐cancer patients." (PMID 35898167, 2023). "The utility of CD24 as an independent prognostic marker of survival has been suggested in patients with ovarian cancer." (PMID 38201468, 2023). "Again, the upregulation of macrophage-derived Siglec-10 at a substantial amount was determined by FACS in the aspect of breast and ovarian cancer cells which elicits a strong affinity of CD24 to interact with Siglec-10 receptor." (PMID 36109471, 2023). "Here, we present an overview of CD24 in ovarian cancer as well as its potential applications in ovarian cancer therapy." (PMID 37359556, 2023). "CD24 plays an important role in the development of anoikis resistance and CD24 can be used as a new therapeutic target to induce anoikis and inhibit metastasis in ovarian cancer." (PMID 36980210, 2023). "Ovarian cancer cells expressing CD24 were found to display greater potential for spreading (metastasis) to intra-abdominal organs in in vivo models." (PMID 38201468, 2023). "Ovarian cancer cells expressed CD24 could achieve the immune evasion through interacting with the receptor called sialic-acid-binding Ig-like lectin 10 (Siglec-10 has been reported to interact with the highly sialylated form of CD24), which is expressed by tumor associated macrophages (TAM)." (PMID 37359556, 2023).
ovarian carcinoma (continued). "Kristiansen reported that the expression of CD24 in cytoplasm is an independent molecular marker for reduced patient survival in ovarian cancer." (PMID 37359556, 2023). "CD24+ cells in ovarian cancer exhibit anoikis resistance, higher tumor growth, colony formation, EMT phenotype and possess stem-like properties such as self-renewal." (PMID 36831617, 2023). "As the study focus more on the relationship between CD24 and ovarian cancer, there are increasing evidence to illuminate the vital role of CD24 in the development of ovarian cancer." (PMID 37359556, 2023). "SWA-11 is a monoclonal antibody that effectively inhibits the growth of lung and ovarian cancer xenografts by targeting CD24." (PMID 37484024, 2023). "CD24, a tumor stem cell marker in ovarian cancer, is involved in the regulation of the epithelial-mesenchymal transition and is a predictor of the clinical outcome." (PMID 37876933, 2023). "It is well demonstrated that the expression of CD24 is related to the development of ovarian cancer in many studies as below." (PMID 37359556, 2023). "Another study reported that a novel anti-CD24 chimeric antigen receptor (CAR) as an immunotherapeutic approach against ovarian cancer cells and cancer stem cells." (PMID 37359556, 2023). "CD24-positive cells isolated from an animal model of ovarian cancer were able to trigger tumorigenesis via JAK2–STAT3 signalling pathways." (PMID 38201468, 2023). "There is a correlation between CD24 expression in primary ovarian cancer tissue and lymph node metastasis, indicating the role of stem cell markers in metastasized OC." (PMID 36831617, 2023). "CD24 has been identified as an independent prognostic marker of survival in patients with ovarian cancer." (PMID 36980210, 2023). "Using nPLEX and ascites samples from ovarian cancer patients, the authors identified exosomal CD24 and EpCAM as biomarkers for ovarian cancer diagnostics." (PMID 36770486, 2023). "Two clinical trials established the clinical safety and acceptability of employing mAbs to inhibit CD24 as a novel and promising strategy for treating breast and ovarian cancer." (PMID 37846296, 2023). "Although the TCGA data showed that almost all the tumors expressed the high level of CD24, the ovarian cancer showed the largest upregulation." (PMID 37359556, 2023). "Rüdiger Klapdor designed a novel third-generation CAR-NK targeting CD24 for the treatment of ovarian cancer, and they selected a single-chain variable fragment (scFv) in SWA11 mAb to be placed on the third-generation CAR backbone." (PMID 38137380, 2023). "The CD24 expression and its significance in Ovarian cancer (OC) tumors have been demonstrated in several studies." (PMID 37919766, 2023). "CD24 is another well-known P-selectin ligand that confers ovarian cancer progression by directly mediating ovarian cancer adhesion to tumor–mesothelial." (PMID 35464064, 2022). "Increased expression of CD24 indicates an increased invasion rate, poor prognosis, and reduced survival rate of patients with ovarian cancer." (PMID 36741380, 2022). "Additional preclinical data support chemoresistance to doxorubicin and cisplatin for CD24+ ovarian cancer and to gemcitabine for CD24+ pancreatic cancer cell lines." (PMID 36013184, 2022). "Recent studies have illustrated that exosomes derived from ovarian cancer contain miRNA, EpCAM, CD24, and other molecules." (PMID 36741380, 2022). "Exosomes release CD24 into the extracellular microenvironment, which can serve as a tumor marker and predict prognosis for ovarian cancer." (PMID 36741380, 2022). "Natural killer (NK) cells have been shown to selectively eradicate less differentiated cells such as CD24+ ovarian cancer cells and cancer stem cells." (PMID 36013184, 2022). "Recently, CD24 was reported as a new ‘don't eat me signal’ which avoids phagocytosis by Siglec10‐expressing macrophages in breast and ovarian cancer, resulting in tumor cell survival." (PMID 35289116, 2022).